EGFEM1P (EGF like and EMI domain containing 1, pseudogene)
Synonyms: formerly C3orf50; NCRNA00259
Gene: Transcribed unitary pseudogene on chromosome 3 (168,249,941 to 168,821,336, forward strand). Ensembl gene ENSG00000206120.
Diseases named in the same sentence as EGFEM1P in open-access papers:
EGFEM1P is named in the same sentence as 2 diseases in open-access papers, as found by Europe PMC text mining. Sharing a sentence is not in itself a finding about the gene and the disease. The quoted sentences say what the papers report.
thyroid cancer (1 paper, 2025). "As for the lncRNA EGFEM1P, it was reported that it promotes thyroid cancer progression by acting as an miR−369−3p sponge and upregulating TCF4." (PMID 40552117, 2025). "EGFEM1P was also reported to be upregulated in papillary thyroid tumors and thyroid cancer cells compared with normal adjacent tissues, and promoted thyroid cancer progression by acting as an miR-369-3p sponge and upregulation TCF4." (PMID 40552117, 2025).
tumor (1 paper, 2018). "Compared with paired normal thyroid tissues, four lncRNAs (LOC100130238, HAND2‐AS1, MIR9‐3HG, and LOC143666) were downregulated in PTC tumor tissues, whereas the remaining four lncRNAs (EGFEM1P, LINC00284, TINCR, and ABCC6P1) were upregulated in PTC tumor tissues." (PMID 30318850, 2018).